STAT3 (signal transducer and activator of transcription 3)
Diseases named in the same sentence as STAT3 in open-access papers (continued):
Sharing a sentence is not in itself a finding about the gene and the disease.
breast cancer (continued). "Despite insufficient evidence, FLT3L/STAT3 cascade directly conducted pDC and anti-tumor immunity via Tcf4 in breast cancer." (PMID 33957948, 2021). "Similar effects have been found in other cancers—namely, IL-6 has been shown to induce the activation of the EMT program via STAT3 activation in breast cancer and to play a role in cancer stemness of osteosarcoma cells via STAT3 activation." (PMID 34063134, 2021). "STAT3 signaling is also essential in PKM2-mediated glucose metabolism in breast cancer cells via the let-7a-5p/Stat3/hnRNP-A1 regulatory feedback loop." (PMID 34887764, 2021). "It was confirmed to reduce breast cancer stem cell load and tumorigenic potential by inhibiting STAT3, FAK and Src mediated pathways and estrogen signaling." (PMID 33391404, 2021). "Our mechanical investigation revealed that circRHOT1 repressed ferroptosis by sponging miR-106a-5p and miR-106a-5p induced ferroptosis by targeting STAT3 in the breast cancer cells." (PMID 33686957, 2021). "STAT3 is not only overactive in different cells of breast cancer milieu, but also simultaneously determines opposite patterns of anti-tumor and pro-tumor immune cells, such as downregulated T cells and upregulated Tregs." (PMID 33957948, 2021). "Pre-clinical data have demonstrated that treatment of HER2+ breast cancer cell models with ruxolitinib decreases STAT3 phosphorylation, decreases tumor growth in vivo and is synergistic when combined with trastuzumab." (PMID 34169393, 2021). "Even the case for STAT3 being a driver of metastasis and tumor growth in breast cancer has been challenged, as there have been studies that have shown both LIF and OSM suppressing tumor growth and metastasis via STAT3 in breast cancer cell lines." (PMID 34395259, 2021). "TAM was also found to promote CSC phenotype and tumorigenesis in breast cancer by activating the EGFR/Stat3/Sox-2 signaling pathway, while inhibition of Sox2 mitigates TAM mediated induction of CSC phenotype and breast tumor growth." (PMID 34207035, 2021). "ZIC2 can be utilized as a useful prognostic indicator in breast cancer and exerts a tumor suppressor effect by regulating STAT3." (PMID 34122521, 2021). "As a result, STAT3 upregulated the expression of breast cancer-aggravating genes, such as CCND1 and MMP2, thereby enhancing the proliferation and migration of breast cancer cells." (PMID 34335938, 2021). "Apart from this, STAT3 inhibition can regulate the production of various immunomodulator factors in TME of breast cancer, such as upregulation of INFs, GM-CSF and IL-2, downregulation of TGF-b, IL-6, and IL-10 proteins." (PMID 33957948, 2021). "Jak/STAT3 increases breast cancer stem cells and cancer chemoresistance by the regulation of lipid metabolism." (PMID 34833950, 2021). "In breast cancer animal model with tumor metastasis, activated STAT3 and higher tumor-specific Tregs population showed co-existence and contributed to immunosuppression." (PMID 33957948, 2021). "Here, we uncover its mechanistic significance by characterizing a novel resistin/LIN28A/Let-7a/IL-6/STAT3 signaling axis supporting the growth and stemness of breast cancer cells." (PMID 34572725, 2021). "Persistent STAT3 activity has been discovered in many cancers, such as breast cancer, colorectal cancer, liver cancer, lung cancer, etc34–36." (PMID 34059647, 2021). "While inhibition of the NOTCH pathway has already been linked to sensitization of glioblastoma or breast cancer cells to radiation, we now show that the NOTCH pathway, controlled by gp130/STAT3 signaling, regulates CRT responsiveness in rectal cancer." (PMID 33530306, 2021). "The MRE11 signaling pathway is not conserved across different cell types, with our prior report indicating that MRE11 mediates its effects in breast cancer via STAT3 and its downstream effectors cyclin D, Myc, and BCL-xL." (PMID 33927349, 2021).
breast cancer (continued). "Collectively, these results unambiguously show that PD-L1 and active forms of STAT3 and NF-κB are strongly expressed in malignant breast cancer cells, but their expression is significantly reduced by NDRG2 overexpression." (PMID 34885221, 2021). "Aberrant JAK2/STAT3 signaling has been reported in various types of tumors, including breast cancer." (PMID 34120621, 2021). "Another co-culture system between macrophages and 4T1 cells revealed that STAT3 was not only activated in macrophages, but also promoted the PD-L1 secretion on macrophages during interaction with breast cancer cells." (PMID 33957948, 2021). "Β-NGF stimulation of untransfected SKBR3 breast cancer cells following starvation induced significant upregulation of pGAS-Luc activity, suggesting that the activation of endogenous TrkA can induce STAT3 nuclear translocation and transcriptional activity." (PMID 34066153, 2021). "Infection of breast cancer cells with STAT3-shRNA reduced STAT3 expression by more than 70% at both the mRNA and protein level." (PMID 33465556, 2021). "The in vitro results showed that Statmp-151 inhibited the proliferation of breast cancer cell lines in a dose- and time-dependent manner and suppressed the phosphorylation of Stat3 in a dose-dependent manner." (PMID 33967793, 2021). "The stimulation of the human breast cancer CD8+ T cells also requires intercellular STAT3 regulation." (PMID 33957948, 2021). "TrkA–STAT3 interaction leads to STAT3 phosphorylation at Y705 by TrkA in breast cancer cells and cell-free kinase assays, indicating that STAT3 is a novel substrate of TrkA." (PMID 34066153, 2021). "Studies showed that breast cancer cell‐derived exosomes (BCC‐Ex) promoted the production of MDSCs in bone marrow to induce immunosuppression through activating STAT3 signalling pathway, thus promoting the invasion and metastasis of breast cancer." (PMID 33955151, 2021). "Combined administration also reduced aberrant nuclear levels of the transcription factor STAT3 and components of its downstream signal pathways, likely underlying the mechanism of lapatinib resistance in HER2-positive breast cancer cells." (PMID 34290605, 2021). "Phosphorylated STAT3 (p-STAT3) leads to tumor progression in a variety of cancers, such as lung cancer, breast cancer, prostate cancer, and melanoma." (PMID 33435880, 2021). "In yet another study, simultaneous inhibition of STAT3 and Tcf4 signaling pathways was reported to suppress the breast cancer cells metastasis both in vitro and in vivo." (PMID 33957948, 2021). "The results of this study suggest that SHOX2 cooperates with STAT3 to drive breast cancer metastasis through upregulating the metastasis-promoting gene WASF3." (PMID 34465361, 2021). "Inhibition of STAT3 activity by ruxolitinib can remarkably inhibit the breast cancer invasion in vivo." (PMID 33957948, 2021). "Pyrimethamine, a direct inhibitor of activated STAT3, conjugated with histone deacetylase inhibitors, also known to inhibit STAT3 activation, has been used successfully in a breast cancer cell line for HDAC and STAT3 pathway inhibition." (PMID 34055801, 2021). "The potential association of HDGF with TKT and STAT3 promotes STAT3-Y705 phosphorylation and inhibits STAT3-S727 phosphorylation enhancing STAT3 transcriptional activity, thereby increasing tumor radioresistance in breast cancer." (PMID 34376200, 2021). "Indeed, we previously showed that an increased ratio of active STAT1/STAT3 in breast tumors is associated with improved immune surveillance, increased production of inflammatory cytokines, and enhanced sensitivity to immune checkpoint inhibitors in breast cancer." (PMID 33807608, 2021). "Accumulating evidence has shown that Stat3 signalling is involved in breast cancer initiation and progression." (PMID 33967793, 2021).
breast cancer (continued). "STAT3 is constitutively activated in cancers, such as ESCC, breast cancer, and lung cancer, which is associated with a poor clinical prognosis, but the mechanism has not been clearly demonstrated." (PMID 33660414, 2021). "This study demonstrates the oncogenic role of MAFF as an activator of the IL11/STAT3 pathways in breast cancer." (PMID 34262028, 2021). "BRK, STAP-2 or STAT3 knockdown all gave similar degrees of reduction in T47D breast cancer cell proliferation." (PMID 33391524, 2021). "In this study, we found that the EGFR and Src-mediated STAT3 signalling pathway was significantly activated in breast cancer cells with acquired resistance to tamoxifen through gene set analysis and protein expression screening." (PMID 34407787, 2021). "They demonstrated that miR-634 suppresses breast cancer cells by targeting STAT3, increasing radiotherapy sensitivity." (PMID 34804940, 2021). "So, the JAK2/STAT3 in CSC is a potential target for developing a successful strategy to improve breast cancer patients’ therapeutic outcomes." (PMID 33672756, 2021). "Targeting the IL20RAhi population with STAT3 signaling inhibition combined with anti-PD-L1 antibody can increase the therapeutic efficacy of chemotherapeutic agents for breast cancer." (PMID 33456560, 2021). "Activation of inflammatory signaling pathways in breast cancer cells induces increases in NF-κB and Stat3 activity, which can drive the formation of breast CSCs." (PMID 33804152, 2021). "Like many breast cancers, these cells also exhibit activation of the STAT3 signaling pathway, which led us to explore the effects of romidepsin in comparison to and in combination with the STAT3 inhibitor Stattic." (PMID 33839684, 2021). "To this end, we applied Gene Set Enrichment Analyses (GSEA) using a STAT3 activation signature, TrkA activation signature, or a combination of STAT3 and TrkA signatures to examine 1533 breast cancer patient samples from TCGA and GEO databases." (PMID 34066153, 2021). "In this study, we investigated the roles of the EGFR and Src-mediated STAT3 signalling pathway in tamoxifen-resistant breast cancer (TamR) cells." (PMID 34407787, 2021). "Another constituent of SB, baicalein attenuated metastatic potential of breast cancer cells by regulating STAT3 activity." (PMID 34068421, 2021). "Another study found that increasing intracellular ROS via the activation of NADPH oxidase complex 5 inhibited breast cancer stemness through the Stat3 signaling pathway in mammospheres." (PMID 33804152, 2021). "RDD648 facilitated STAT3 translocation to the nucleus, and this was involved in lysosomal-mediated cell death in breast cancer cells." (PMID 34822366, 2021). "Vice versa, mesenchymal derived cells can induce STAT-3 signaling in breast cancer cell lines via IL-6, thereby enhancing breast cancer cell growth in vitro and in vivo." (PMID 33809315, 2021). "miR-34a and Let-7b were reported repressed by STAT3 signaling in colon cancer and breast cancer cells." (PMID 33942213, 2021). "Constitutive activation of STAT3 has frequently been observed in a variety of tumours, including breast cancer, and such activation can promote proliferation and survival of cancer cells." (PMID 33806019, 2021). "In breast cancer, the imperative role of STAT3 as the mediator of EMP induction by IL-6 family is well accepted." (PMID 34361105, 2021). "Previous studies have shown that STAT3 promotes PD-L1 expression, contributing to chemoresistance of breast cancer, head, and neck squamous cell carcinoma, and non-small-cell lung cancer." (PMID 34321456, 2021). "The reason for its positive relationship with prognosis in breast cancer is because in this cancer, Zic2 directly represses STAT3 transcription." (PMID 34099631, 2021). "JAK1 modulates oncogenic activation of STAT3 in mammary cancer cells driven by ERBB2 receptor tyrosine kinase signaling." (PMID 34455105, 2021).
breast cancer (continued). "Our study has elucidated the molecular mechanism through which BQ can modulate the expression of IL-6 and IL-6R and thus the activation of STAT3 in breast cancer." (PMID 33806019, 2021). "This was confirmed in breast cancer, and PTPRT was negatively associated with STAT3, while the promoter methylation level of PTPRT was positively associated with STAT3 based on TCGA data." (PMID 34414233, 2021). "To further investigate the mechanism of anisomycin inducing apoptosis, we used western blot to detect the STAT3/p-STAT3 expression after the treatment of anisomycin in human breast cancer cell lines (i.e., MDA-MB-231, MDA-MB-436, BT549, and Hs578T)." (PMID 33768099, 2021). "To further validate the result, we analyzed tissue specimens from HMUCC, and we found that EGFR, JAK2, and STAT3 were upregulated in breast-cancer tissues relative to the expression in normal tissues." (PMID 33446634, 2021). "The results indicated that anisomycin was a potent inhibitor of STAT3 in human breast cancer cell lines." (PMID 33768099, 2021). "Highly enriched of glycoprotein 130 (gp130) from breast cancer (BC)-derived exosomes triggers the secretion of interleukin-6 (IL-6) and activate the IL-6/STAT3 pathway." (PMID 34722637, 2021). "Luteolin has a synergistic effect with paclitaxel, which can effectively reduce p-STAT3 in mouse breast cancer cells and induce breast tumor regression in mice injected subcutaneously with MDA-MB-231 cells together with paclitaxel." (PMID 34539403, 2021). "We aimed to investigate the role of the EGFR and Src-mediated STAT3 signalling pathway in tamoxifen-resistant breast cancer cells." (PMID 34407787, 2021). "It is now thought that tumor-derived factors (TDFs) IL-6, VEGF, and G-CSF secreted by tumor itself in TME of breast cancer have the ability to stimulate STAT3 cascade in myeloid cells differentiation." (PMID 33957948, 2021). "In late stage breast cancer tissues, transient expression of miR-181b is activated by STAT3, a transcription factor activated by IL-6, which results eventually in upregulation of NF-kB and downregulation of let-7a." (PMID 33901254, 2021). "In conclusion, we concluded that circNOLC1 contributed to CSCs properties and progression of breast cancer by targeting miR-365a-3p /STAT3 axis and propofol inhibited circNOLC1 by repressing STAT3 in a feedback mechanism." (PMID 34789263, 2021). "In the same way, our results confirm that canine mammary cancer cells showed an equivalent response to CT treatment, and the addition of a selective STAT3 inhibitor enhanced cell death emphasizing the biological and genetic resemblance to human breast cancer." (PMID 33544704, 2021). "For example, the JAK/STAT3-mediated regulation of lipid metabolism is essential for breast cancer stem cell (BCSC) self-renewal and cancer chemoresistance." (PMID 33823894, 2021). "Our data suggest that the GLI1 gene, also activated by STAT3 in breast cancer cells, can be activated by either phosphoserine or phosphotyrosine STAT3." (PMID 33747356, 2021). "For instance, Yeo and collaborators showed that autophagy performs via EGFR/Stat3 and Tgfβ/Smad signaling in two breast cancer stem-like cells (ALDH+and CD29hiCD61+, respectively)." (PMID 33477367, 2021). "In particular, smoking promotes chemotherapy-resistant and anti-apoptotic effects on breast cancer cells by signaling cascades of STAT3, galectin-3, and nicotine acetylcholine receptors." (PMID 34796198, 2021). "Consistent with our results, another two cardiac glycosides, oleandrin and odoroside A, have been reported to inhibit STAT3 activation in breast cancer cell line." (PMID 34277430, 2021). "The mitochondrial localization of STAT3 is required for its ability to support malignant transformation in breast cancer cells." (PMID 34376200, 2021).
breast cancer (continued). "STAT3 signaling is known to be selectively activated in BCSCs, suggesting that targeting the STAT3 signaling pathway using phytochemicals is a potential direction to suppress BCSCs for treating breast cancer." (PMID 34948368, 2021). "For instance, the IL‐6/STAT3 signaling axis contributes to the growth of stem cell‐like breast cancer growth." (PMID 33605027, 2021). "Isoharringtonine (IHT), a natural analogue of HHT, was found to have functional of decreasing the proliferation, migration, and breast cancer stem cell proportion via inhibition of the STAT3/Nanog pathway." (PMID 33867824, 2021). "PL is effective in inhibiting STAT3 and inhibiting proliferation progression in breast cancer cell lines." (PMID 34975915, 2021). "The clinical correlation of circNOLC1/miR-365a-3p/STAT3 axis and other targets of circNOLC1 and miR-365a-3p in the regulation of breast cancer should be explored by more investigations." (PMID 34789263, 2021). "EZH2 over-expressed in breast cancer patients and regulated STAT3 post-transcriptionally according to TCGA datasets." (PMID 34335938, 2021). "Signal transducer and activator of transcription 3 (Stat3) is overexpressed and hyperactivated in a variety of human tumours, including breast cancer, thus representing a promising target for breast cancer treatment." (PMID 33967793, 2021). "MDSCs are also reported to endow stem-like qualities to breast cancer cells through IL6/STAT3 and NO/Notch cross-talk signaling." (PMID 35003065, 2021). "For the upstream, reactive oxygen species (ROS) and IL-6 triggered STAT3 activation regulates MDSCs expansion in the breast cancer, which are both typical characteristics of MDSCs." (PMID 33957948, 2021). "Primaquine and CQ induce the apoptosis of breast cancer through nEGFR/Stat3-dependent c-Myc downregulation, which provides a strategy for the treatment of breast cancer by targeting the EGFR signaling components." (PMID 34884765, 2021). "A recent study found that inactivating mutations in metastatic/relapsed breast cancer cells preferentially target the genes JAK2 and STAT3, and more in general, the JAK-STAT signaling pathway." (PMID 34568068, 2021). "13R,20-diHDHA deregulates this equilibrium through dephosphorylation of Stat3 and deregulation of IL-6, and thereby reduces the cancer stemness of breast cancer cells." (PMID 33804152, 2021). "Collectively, our data suggest that VCAN-AS1 is upregulated in breast cancer and promotes its progression by regulating the miR-106a-5p-mediated STAT3/HIF-1α pathway." (PMID 34365889, 2021). "An in vitro study showed that MSCs inhibit cell cycle progression in breast cancer cells and promote apoptosis by downregulating the Stat3 signalling pathway." (PMID 33860061, 2021). "It has been shown that induction of STAT3 via FGFR2/STAT3 signaling axis correlated with more aggressive breast cancer." (PMID 34858425, 2021). "Here, we determined that the level of S1PR1 in breast cancer cells is positively correlated with STAT3 activation and VEGFA expression." (PMID 34059068, 2021). "MiR-365a-3p targeted signal transducer and activator of transcription 3 (STAT3) in breast cancer cells and circNOLC1 enhanced STAT3 expression by sponging miR-365a-3p." (PMID 34789263, 2021). "IL-6 has been reported to be present in higher levels in CM2D than in CM3D and has also been associated with the stimulation of the migration of breast cancer cells by induction of AKT, MAPK and STAT3 phosphorylation." (PMID 34884877, 2021). "In detail, the S727 phosphorylation of STAT3 was fundamental for the full transcriptional activation of cyclinD1 gene (a key cell cycle regulator in breast cancer) through pSTAT3 S727 recruitment on its promoter." (PMID 34440160, 2021). "This study identifies the molecular mechanisms through which BQ323636.1 can enhance IL-6 and IL-6R expression, which leads to the activation of STAT3 and the development of tamoxifen resistance in ER+ breast cancer." (PMID 33806019, 2021).